EGFR (epidermal growth factor receptor)
Diseases named in the same sentence as EGFR in open-access papers (continued):
Sharing a sentence is not in itself a finding about the gene and the disease.
meningitis (9 papers, 2015 to 2024). A disorder characterized by acute inflammation of the meninges of the brain and/or spinal cord. "In a previous publication we have shown the Gram-positive bacterium S. suis, which possesses the zoonotic potential and the ability to cause meningitis, was able to transactivate host EGFR for the development of neuroinflammatory response in BMECs." (PMID 30687645, 2018). "Together, these data support our novel concept that EGFR contributes to meningitis-causing E. coli penetration of the BBB." (PMID 27711202, 2016). "Additionally, as we have found that EGFR activation by the meningitis-causing S. suis type 2 strain also occurs, we have increasingly wondered whether this mechanism also exists during S. suis invasion of BMECs." (PMID 30687645, 2018). "As far as we are aware, this is the first report of EGFR-TKI efficacy for carcinomatous meningitis in a NSCLC patient harboring EGFR-KDD." (PMID 34240806, 2021). "Here, we report the case of a 45-year-old Japanese woman with NSCLC positive for EGFR-KDD (duplication of exons 18-25) who developed carcinomatous meningitis and showed a marked response to the EGFR-TKIs erlotinib and osimertinib." (PMID 34240806, 2021). "More significantly, all vital biotargets of calycosin-anti-meningitis were eventually identified, including EGFR, TNF, EGF, ATM, ESR1, CASP8, NGF." (PMID 33031061, 2020). "Our study indicated that patients with limited BMs in the upfront TKI group were more likely to develop meningeal metastases and multiple BMs at the first cranial progression during the treatment of EGFR-TKIs and thus losing the opportunity of SRS in salvage RT." (PMID 37759881, 2023). "Notably, this strategy involving activated EGFR competing with F-actin for ACTN4 to disrupt the cytoskeleton is exploited not only by meningitic E. coli K1 and K2 strains, but also by meningitis-causing S. suis strains." (PMID 30687645, 2018). "Thus, altogether, our observations supported that EGFR plays an important role in SS2 strain SC19-induced meningitis, in which it can influence the SS2 induction of the cytokines and chemokines in the brain." (PMID 27756321, 2016). "However, the specific role of EGFR in SS2 infection, especially its association with SS2-induced meningitis, is completely unclear." (PMID 27756321, 2016). "We found an important role of EGFR in SS2 strain SC19-induced meningitis." (PMID 27756321, 2016). "One patient (No. 15) harboring EGFR exon 21 point mutation developed multiple brain metastases and carcinomatous meningitis immediately after chemoradiotherapy and was then treated with best supportive care without EGFR-TKI because of poor general condition." (PMID 26682906, 2015). "Therefore, we used a K2-capsular E. coli strain (PCN033) isolated from the cerebrospinal fluid of a case of porcine meningitis, to explore the potential function as well as the detailed mechanism of the EGFR-ACTN interaction in bacterial penetration of the BBB." (PMID 30687645, 2018). "Whether and how EGFR contributes to the development of S. suis meningitis are currently unknown." (PMID 27756321, 2016). "In this report, we demonstrate a novel role of EGFR in E. coli penetration of the BBB, a prerequisite for the development of E. coli meningitis." (PMID 27711202, 2016). "We, then, showed that EGFR contributed to E. coli penetration of the BBB, indicating that our approach of targeting E. coli invasion of HBMEC is likely to identify targets involved in the pathogenesis of E. coli meningitis." (PMID 27711202, 2016). "This EGFR transactivation triggers the downstream MAPK-ERK1/2 pathway, as well as NF-κB signaling, both of which mediate the production of proinflammatory cytokines and chemokines in the host brain, thus contributing to neuroinflammation and the development of SS2 meningitis." (PMID 27756321, 2016).
meningitis (continued). "To clarify the effects of EGFR in SS2-induced meningitis, we first investigated the adhesion of SS2 strain SC19 to hBMEC, with or without pretreatment of the EGFR inhibitor AG1478." (PMID 27756321, 2016).
oligodendroglial tumor (9 papers, 2010 to 2025). Oligodendrogliomas are cerebral tumors that are differentiated from other gliomas on the basis of their unique genetic characteristics and better response to chemotherapy. "Although the absence of 1p/19q deletion is a consistent feature of scGBM, the presence of EGFR amplification differentiates it from oligodendroglial tumors." (PMID 40058218, 2025). "In oligodendroglial tumors, it was strongly associated with both IDH1/IDH2 mutations and total 1p/19q codeletion and inversely with EGFR gene amplification." (PMID 24083241, 2013). "In oligodendroglial tumors, it is strongly associated with both IDH1/IDH2 mutations and total 1p/19q codeletion and inversely with EGFR gene amplification." (PMID 24083241, 2013). "Finally, the significant association between NG2/CSPG4 immunoreactivity and EGFR gene amplification (a well-known negative prognostic marker) in both astrocytic and oligodendroglial tumors is in line with previous findings." (PMID 32599896, 2020). "Even if the “classic profile” was not prevalent (∼15%) in AO, as compared to the proneural one (∼75%), this subclass allowed to distinguish oligodendroglial tumors with neither 1p/19q co-deletion nor IDH1 mutations but with EGFR gene amplification and chromosome 10 loss." (PMID 23874590, 2013).
pituitary tumor (9 papers, 2012 to 2025). A benign or malignant neoplasm affecting the pituitary gland. "The study also proposed that CABLES1 mutations could represent a novel pituitary tumor-predisposing mechanism, particularly affecting interactions with cyclin-dependent kinases (CDKs) and the epidermal growth factor receptor (EGFR) pathway." (PMID 40364036, 2025). "EGFR, crucial for corticotroph function, is highly expressed in Cushing’s pituitary tumors and stimulates ACTH synthesis." (PMID 38275385, 2023). "There are likely to be other, currently unidentified, factors that may also contribute to EGFR signaling in pituitary tumors." (PMID 32012988, 2020). "Finally, to validate that Cushing phenotype was due to the EGFR upregulation, these transgenic mice were treated with an EGFR inhibitor, such as gefitinib: Treated mice displayed a diminished pituitary tumor size and lower plasma glucose levels." (PMID 31487906, 2019). "Therefore, the results obtained by the analysis of the corti-EGFR-Tg mouse model support previous findings indicating that EGFR1 activity is mediated by E2F1 and EGFR1 overexpression is associated with aggressive pituitary tumors." (PMID 31487906, 2019). "Research using human pituitary adenomas and some invasive pituitary tumors has revealed expression of EGF and/or EGFR." (PMID 29255445, 2017). "Upregulated gene expression of cognate receptors of these growth factors, i.e., EGFR, FGFR1, and FGFR3, was detected in the human pituitary tumor SP, suggesting that EGF/FGF signaling may function to drive cell proliferation in these candidate TSC." (PMID 29255445, 2017).
polycystic kidney disease (9 papers, 2012 to 2025). A usually autosomal dominant and less frequently autosomal recessive genetic disorder characterized by the presence of numerous cysts in the kidneys leading to end-stage renal failure. "An inhibitor of EGFR tyrosine kinase was also effective as a treatment for polycystic kidney disease by reducing cystic lesions." (PMID 32432044, 2020). "Some studies have demonstrated that the TGFα/EGFR autocrine loop plays an important role in polycystic kidneys and pancreatic neoplasms." (PMID 32432044, 2020). "EGFr also modulates the formation of cellular cysts in polycystic kidney disease, which further supports the results in our study." (PMID 29508172, 2018). "Expression of the EGFR is increased in polycystic kidney disease (PKD) renal tissue." (PMID 36914219, 2023). "Thus, targeting HDAC6 to downregulate EGFR and its downstream targets as well as to normalize its localization from apical to basolateral may be a potential therapeutic approach for polycystic kidney disease." (PMID 23152903, 2012). "Thus, targeting HDAC6 to downregulate EGFR and also normalize EGFR localization may be a potential therapeutic approach to treat polycystic kidney disease." (PMID 23152903, 2012). "Thus, targeting HDAC6 to downregulate EGFR activity may provide a potential therapeutic approach to treat polycystic kidney disease." (PMID 23152903, 2012). "Some experimental studies have reported deleterious effects of EGFR activation in ADPKD, since EGFR blockade improved experimental progressive (polycystic) kidney disease [7, 8, 22 and 23]." (PMID 36914219, 2023). "Tesevatinib is an inhibitor of EGFR, HER2, VEGFR and ephrin B4, used in polycystic kidney disease and tested as monotherapy in GBM (NCT02844439)." (PMID 33918704, 2021). "Lcn-2 induces cell proliferation via EGFR activation in non-inflammatory polycystic kidney disease models." (PMID 23861783, 2013).
preeclampsia (9 papers, 2012 to 2025). Preeclampsia is a hypertensive disorder of pregnancy that is characterized by new-onset hypertension with proteinuria presenting after 20 weeks of gestation, and depending on mild or severe forms may initially present with severe headache, visual disturbances, and hyperreflexia. "ATF3 and EGFR were implicated as the main regulators of preeclampsia development in our previous integrative transcriptome analysis." (PMID 24885447, 2014). "Decreased expression of placental EGFR has been shown to be associated with obstetrical complications: placental expression of full-length EGFR mRNA transcript is decreased in IUGR while in preeclampsia, placental and plasma EGF levels are reduced." (PMID 29666409, 2018). "We also conducted an analysis of ENCODE Chip Seq data to infer common transcription regulatory networks of selected genes (such as TTD genes and GTF2E1) and gene regulators (such as EGFR, ATF3, and FLT1) implicated in preeclampsia." (PMID 24885447, 2014). "Our subsequent integrative transcriptome analysis shed further light on the link between impairment of TFIIH-mediated functions in placenta and induction of molecular mediators of clinical symptoms of preeclampsia through dysregulation of EGFR- and ATF3-dependent pathways." (PMID 24885447, 2014). "Regarding the potential of markers for discriminating preeclampsia patients from normal pregnant women, the ROC analysis revealed that the AUC values of the NQO1, SRXN1, CDO1, EGFR, FBXW7, and JUN are 0.803, 0.748, 0.708, 0.703, 0.665, and 0.681, respectively." (PMID 36061193, 2022). "In preeclampsia patients, p110/EGFR (a truncated epidermal growth factor receptor isoform) has also been reported to be elevated." (PMID 28542650, 2017). "For example, Flt-1, HtrA, Calretinin, PAI-1 and EGFR were positively and PDEF, Annexin XI, PLGF and PCNA were inversely correlated with the severity of preterm preeclampsia." (PMID 25392996, 2014). "In this group, EGFR and GRB2, are both with highest scores and there are both well related with preeclampsia." (PMID 22873350, 2012). "Among 167 proteins tested, the expression of 5 proteins (EGFR, Flt-1, Calretinin, PAI-1 and HtrA) were positively correlated and four proteins (AnnexinXI, PDEF, PCNA and PlGF) were inversely correlated with the severity of preterm preeclampsia (P<0.05, R value≥0.4)." (PMID 25392996, 2014).
steatosis (9 papers, 2015 to 2025). Increased lipid within the cytoplasm of cells. "In addition, EGFR inhibitor-mediated reduction of hepatic PPARγ activity (mainly in hepatocytes) was associated with reduced and reversed steatosis and fibrosis in a mouse model of NASH induced with fast food diet." (PMID 32411189, 2020). "Our study demonstrated that in vitro, knockdown of EGFR attenuated PA-induced hepatocellular steatosis, and on this basis, the therapeutic role of lycorine in steatosis was limited." (PMID 39604837, 2024). "EGFR inhibition attenuated steatosis by regulating key transcription factors regulating fatty acid synthesis and lipolysis in NAFLD mouse models." (PMID 36077090, 2022). "Recently, EGFR inhibition prevented the development of steatosis and liver injury in a mouse model of NAFLD." (PMID 33806040, 2021). "In vitro, knockdown of EGFR significantly attenuated palmitic acid-induced hepatocyte steatosis." (PMID 39604837, 2024). "Another is PD98059, an ERK inhibitor, as we hypothesized that the effect of EGFR inhibition on hepatic steatosis may be mediated by MEK/ERK." (PMID 35886933, 2022). "EGFR is found to regulate NAFLD at various stages, starting from steatosis to NASH, and even with regard to fibrosis, while other RTKs discussed, such as AXL, FGFR4 and VEGFR, are also found to be effective in regulating different manifestations of NAFLD." (PMID 34944593, 2021).
Alpha-thalassemia (8 papers, 2023 to 2025). Alpha-thalassemia is an inherited hemoglobinopathy characterized by impaired synthesis of alpha-globin chains leading to a variable clinical picture depending on the number of affected alleles. "These markers include mutations in phosphatase and tensin homolog (PTEN), alpha-thalassemia/mental retardation syndrome X-linked (ATRX), and telomerase reverse transcriptase (TERT), as well as CDKN2A/B homozygous deletions and epidermal growth factor receptor (EGFR) amplification." (PMID 40218147, 2025).
benign prostatic hyperplasia (8 papers, 1989 to 2025). A non-cancerous nodular enlargement of the prostate gland. "Our previous studies demonstrated that the prostaglandin synthase, cyclooxygenase-2 (COX-2), could mediate the progress of prostatic hypertrophy in rats treated with BPA (10, 30, 90 μg/kg/day), accompanying the overexpression of the epidermal growth factor receptor (EGFR)." (PMID 36293141, 2022).
bronchioalveolar carcinoma (8 papers, 2004 to 2024). "There is a case of multiple adenocarcinomas in situ of the lung having the same mutation of EGFR in common." (PMID 23617234, 2013). "Adenocarcinoma in situ of the lung was frequently associated with EGFR gene mutation." (PMID 23617234, 2013). "Of importance, the frequency of EGFR mutation in patients with bronchioalveolar carcinoma was similar to that seen in patients with non-BAC adenocarcinomas." (PMID 15942627, 2005). "Interestingly, two weeks after doxycycline indication, the EGFR L8585R mutants showed diffuse lung cancer that resembled human bronchioalveolar carcinoma in contrast to the mutant-deletion mice (EGFR DeltaL747-S752) that developed multifocal tumors embedded in normal lung parenchyma." (PMID 39796653, 2024).
Cerebral ischemia (8 papers, 2015 to 2025). Restriction of arterial blood supply to the brain associated with insufficient oxygenation to support the metabolic requirements of the tissue. "The core intersecting targets between cerebral ischemia and TB-2 are EGFR, SRC, GSK3B, MAPK1, and KDR, which may serve as potential therapeutic targets." (PMID 39376614, 2024). "During brain ischemia/reperfusion, EGFR could be transactivated, which stimulates these intracellular signaling cascades that either protect cells or potentiate cell injury." (PMID 26442853, 2015). "In the present study, the role of EGFR in neuroinflammation was investigated using oxygen/glucose deprivation (OGD), a well known in vitro model of brain ischemia." (PMID 30792526, 2019). "Epidermal growth factor receptor showed anti-apoptotic effects by activation of the PI3K/AKT pathway in one study with undifferentiated SH-SY5Y and one study with differentiated SH-SY5Y cell models of cerebral ischemia." (PMID 37380886, 2023). "Inhibitors of ROS, PTEN, EGFR, and ERK may have therapeutic potential in clinic for brain ischemia." (PMID 26442853, 2015). "A pathological role of EGFR signaling has been demonstrated in CNS neurodegenerative diseases, including SCI, AD, brain ischemia and subarachnoid hemorrhage but not ICH." (PMID 40444141, 2025).
ductal carcinoma (8 papers, 2013 to 2023). "In addition, myoepithelial markers, particularly p63, and EGFR are more frequently expressed in MpBC (approximately 70–80%) than in ductal carcinoma." (PMID 37218987, 2023). "In addition to the histologic resemblance, SDC is similar to breast ductal carcinoma regarding overexpression of ERBB2 and EGFR in many cases." (PMID 25343854, 2014).
endometrial adenocarcinoma (8 papers, 2010 to 2022). "We have shown activation of the EP2 and FP receptors can lead to phosphorylation of ERK1/2 via the activation of c-Src and transphosphorylation of the epidermal growth factor receptor (EGFR) in Ishikawa cells and endometrial adenocarcinoma explants ex vivo." (PMID 19782748, 2010). "Induction of CCL20 by PGF-2α/FP signaling in an endometrial adenocarcinoma cell line was found to be dependent on intracellular signaling by Gq protein, epidermal growth factor receptor (EGFR), extracellular signal-regulated kinase (ERK), calcineurin, and nuclear factor of activated T cell (NFAT)." (PMID 35408440, 2022). "PGE2 stimulates vascular endothelial growth factor (VEGF) expression in Ishikawa cells (a human endometrial adenocarcinoma cell line) via EP2-cAMP-mediated transactivation of the epidermal growth factor receptor (EGFR) and extracellular signal-regulated kinases 1/2 (ERK1/2) pathways." (PMID 32363546, 2020). "Furthermore, elucidation of the detailed mechanistic events by which LRIG2 acts as a novel upstream regulator of PI3K/AKT and EGFR in endometrial adenocarcinoma is needed." (PMID 29358688, 2018). "GPER and EGFR expression were correlated in endometrial adenocarcinoma." (PMID 23273253, 2012). "Conversely, it has been reported that the presence of truncated EGFR isoforms may be predictive of the therapeutic response to gefitinib in endometrious adenocarcinomas." (PMID 22159595, 2012). "Besides, Dae-Shik Suh and his colleagues reported that LRIG2 was a tumor suppressor gene in endometrial adenocarcinoma and inhibited cell growth through regulating PI3K/AKT and EGFR." (PMID 32863771, 2020).